CDC16 (cell division cycle 16)
Description:
Component of the anaphase promoting complex/cyclosome (APC/C), a cell cycle-regulated E3 ubiquitin ligase that controls progression through the cell cycle. APC/C acts by mediating ubiquitination and subsequent degradation of target proteins: it mainly mediates the formation of 'Lys-11'-linked polyubiquitin chains and, to a lower extent, the formation of 'Lys-48'- and 'Lys-63'-linked polyubiquitin chains. APC/C complex catalyzes assembly of branched 'Lys-11'-/'Lys-48'-linked branched ubiquitin chains on target proteins. APC/C is activated by CDC20 in the metaphase/anaphase transition of cell cycle, targeting the degradation of cyclin B and securin. APC/C is regulated by the mitotic checkpoint complex (MCC), which inhibits APC/C and delays chromosome segregation.
Synonyms: APC6; CDC16Hs; ANAPC6; CUT9
Tractability: PROTAC: ubiquitination databases record sites on it; its protein half-life has been measured.
Gene: Protein-coding gene on chromosome 13 (114,234,856 to 114,272,723, forward strand). Ensembl gene ENSG00000130177.
Subcellular location: Cytoplasm, cytoskeleton, microtubule organizing center, centrosome; Cytoplasm, cytoskeleton, spindle
Pathways (Reactome):
Cell Cycle: APC-Cdc20 mediated degradation of Nek2A; APC/C:Cdc20 mediated degradation of Cyclin B; APC/C:Cdc20 mediated degradation of Securin; APC/C:Cdc20 mediated degradation of mitotic proteins; APC/C:Cdh1 mediated degradation of Cdc20 and other APC/C:Cdh1 targeted proteins in late mitosis/early G1; Autodegradation of Cdh1 by Cdh1:APC/C; Cdc20:Phospho-APC/C mediated degradation of Cyclin A; Conversion from APC/C:Cdc20 to APC/C:Cdh1 in late anaphase; Inactivation of APC/C via direct inhibition of the APC/C complex; Phosphorylation of the APC/C; Regulation of APC/C activators between G1/S and early anaphase; Separation of Sister Chromatids
DNA Replication: Assembly of the pre-replicative complex; CDK-mediated phosphorylation and removal of Cdc6
Cellular responses to stimuli: Senescence-Associated Secretory Phenotype (SASP)
Disease: Aberrant regulation of mitotic exit in cancer due to RB1 defects
Gene expression (Transcription): Transcriptional Regulation by VENTX
Immune System: Antigen processing: Ubiquitination & Proteasome degradation
Gene Ontology:
Molecular function: protein binding; enzyme-substrate adaptor activity
Biological process: anaphase-promoting complex-dependent catabolic process; protein branched polyubiquitination; protein K11-linked ubiquitination; protein K48-linked ubiquitination; cell division; positive regulation of mitotic metaphase/anaphase transition; protein ubiquitination; regulation of meiotic cell cycle; regulation of mitotic cell cycle
Cellular component: anaphase-promoting complex; centrosome; cytoplasm; mitotic spindle; cytosol; nucleoplasm; nucleus; spindle
Genetic constraint (gnomAD): Loss-of-function variants: 22 observed, 47.82 expected, observed/expected ratio (o/e) 0.46, 90% interval 0.33 to 0.66. The upper end of that interval is the gene's LOEUF score, 0.66, which puts it in group 2 of 6, group 1 being the genes least tolerant of losing a copy. Missense variants: 396 observed, 471.42 expected, observed/expected ratio (o/e) 0.84, 90% interval 0.77 to 0.91. Synonymous variants: 166 observed, 164.12 expected, observed/expected ratio (o/e) 1.01, 90% interval 0.89 to 1.15.
Homologues: Orthologues: chimpanzee CDC16 (100% identical), macaque CDC16 (99% identical), pig CDC16 (98% identical), dog CDC16 (98% identical), guinea pig CDC16 (97% identical), rat Cdc16 (96% identical), mouse Cdc16 (95% identical), tropical clawed frog cdc16 (89% identical), rabbit CDC16 (88% identical), zebrafish cdc16 (80% identical), Drosophila melanogaster Cdc16 (42% identical), Caenorhabditis elegans emb-27 (24% identical). Paralogues in human: CDC27 (20% identical), CDC23 (16% identical), ANAPC7 (15% identical).
Diseases named in the same sentence as CDC16 in open-access papers:
CDC16 is named in the same sentence as 26 diseases in open-access papers, as found by Europe PMC text mining. Sharing a sentence is not in itself a finding about the gene and the disease. The quoted sentences say what the papers report.
breast carcinoma (4 papers, 2014 to 2023). "CDC16 has been reported as a binding partner of chitooligosaccharide deacetylase homolog (YDJC) in breast cancer cells." (PMID 33051402, 2020). "CDC16 encodes a component of the APC complex, which is a cyclin degradation system that governs exit from mitosis and has been with an altered risk of breast cancer." (PMID 25148247, 2014). "Furthermore, CDC16 has been proposed as a binding partner of YDJC in breast cancer cells." (PMID 29796162, 2018). "Since previous studies have shown that DEPDC1B promotes angiogenesis and metastasis of melanoma by competing with CDC16 to promote SCUBE3 secretion, we investigated whether a similar phenomenon exists in breast cancer." (PMID 37642235, 2023).
lung carcinoma (4 papers, 2016 to 2020). "Kim and coworkers reported that suppression of YDJC or boosting of CDC16 interaction with YDJC might be implicated in the progression of lung cancer." (PMID 33051402, 2020). "We also proposed the novel mechanism of CDC16/YDJC/PP2A/ERK2 in lung cancer progression although it is necessary to confirm the proposed mechanism of the scheme." (PMID 31485224, 2019). "We found that YDJC induced EMT via ERK2 activation by PP2A downregulation through ubiquitination leading to the promotion of the progression of lung cancer and CDC16 reversed this by directly interacting with YDJC leading to ubiquitination." (PMID 31485224, 2019). "The collective findings indicate that YDJC is involved in SPC-induced events in A549 lung cancer cells by binding to CDC16." (PMID 29796162, 2018). "The collective results indicate that YDJC is involved in SPC-induced events in A549 lung cancer cells by interacting with CDC16." (PMID 29796162, 2018). "siRNA of CDC16 induced phosphorylation and reorganization of K8, migration, and invasion of A549 lung cancer cells." (PMID 29796162, 2018). "Furthermore, progression-free survival in lung cancer patients with ‘YDJC-high and CDC16-low’ showed higher HR value and improved p-value compared to lung cancer patients with YDJC-high (increase from 1.43 to 1.5 and decrease from 0.01 to 0.0016)." (PMID 29796162, 2018). "Curiously, CDC16 gene silencing induced EMT, migration, and invasion, even without SPC treatment in lung cancer cell lines." (PMID 31485224, 2019).
melanoma (4 papers, 2020 to 2023). A malignant, usually aggressive tumor composed of atypical, neoplastic melanocytes. "It is worth noting that it was reported that DEPDC1B promotes SCUBE3 secretion through competitive binding with ubiquitin ligase CDC16, thus promoting angiogenesis and metastasis of melanoma." (PMID 37642235, 2023). "This study unravels a new molecular mechanism of DEPDC1B acting downstream of SOX10 to promote melanoma angiogenesis and metastasis through CDC16 sequestration that stabilizes secreted SCUBE3, which suggests the possibility of targeting SCUBE3 as a therapeutic strategy against metastatic melanoma." (PMID 35088579, 2022). "It has been found that CDC16 has potential therapeutic function in melanoma." (PMID 34970268, 2021). "DEPDC1B competitively interacts with CDC16 in the cytosol to block the ubiquitination and degradation of SCUBE3, enabling stabilized SCUBE3 to be secreted from melanoma cells for blood vessel recruitment to facilitate their growth, survival, and metastasis." (PMID 35088579, 2022). "In addition, immunofluorescence staining in melanoma tissue arrays showed that expression levels of SOX10, DEPDC1B and CDC16 were high in nevi which do not metastasize but SCUBE3 was barely detectable." (PMID 35088579, 2022).
colon cancer (3 papers, 2005 to 2022). "Gene alterations in several components of the APC/C complex, including APC6/CDC16 and APC8/CDC23, have been found in human colon cancers." (PMID 27030811, 2015).
gastric cancer (2 papers, 2020). A primary or metastatic malignant neoplasm involving the stomach. "To understand the mechanism underlying the cell cycle arrest of gastric cancer cells induced by knocking down AURKB, we next examined the effect of AURKB on various key cell cycle regulatory molecules, including CCND1, CDC16, CDC6, CDC26, CCNB2, CCNF, p27 and E2F1, in gastric cancer cells." (PMID 31982864, 2020).
colorectal cancer (1 paper, 2018). A primary or metastatic malignant neoplasm that affects the colon or rectum. "Two mRNAs (E2F5 and CDC16) that were associated with altered colorectal cancer survival were associated with six of the miRNAs associated with altered colorectal cancer survival: hsa-miR-15a-5p, hsa-miR-17-5p, hsa-miR-19b-3p, hsa-miR-20a-5p, hsa-miR-20b-5p, and hsa-miR-92a-3p." (PMID 29725503, 2018).
deafness (1 paper, 2021). An inherited or acquired condition characterized by the complete loss of the ability to hear from one or both ears. "Abnormal expression of CDC16 can lead to diseases such as deafness and early infantile epileptic encephalopathy." (PMID 33978759, 2021).
hearing loss (1 paper, 2016). "OXR1 contains the Tre2/Bub2/Cdc16 (TBC), lysin motif (LysM), domain catalytic (TLDc) domain, a motif present in a family of proteins including TBC1 domain family member 24 (TBC1D24), a protein mutated in a range of disorders characterized by seizures, hearing loss, and neurodegeneration." (PMID 26668325, 2016).
hepatocellular carcinoma (1 paper, 2015). A malignant tumor that arises from hepatocytes. "These genes include: transcription factor Dp-1 (TFDP1), cullin 4A (CUL4A), and cell division cycle 16 (CDC16) identified in hepatocellular carcinoma (HCC), breast cancer, and lung cancer; and insulin receptor substrate 2 (IRS2) present in colorectal cancer." (PMID 26684807, 2015).
intestinal tumor (1 paper, 2020). "For CDC16, we found only protein levels with a significant increase in intestinal tumor samples (p = 0.015)." (PMID 33351778, 2020).
metastatic melanoma (1 paper, 2022). A melanoma that has spread from its primary site to another anatomic site. "As expected, CDC16 was ubiquitously expressed in all the analyzed specimens, but we detected a positive correlation between SOX10 and SCUBE3 expressions in metastatic melanomas (n = 19/22)." (PMID 35088579, 2022).
neuroblastoma (1 paper, 2025). Neuroblastoma (NB) is the most common solid, extracranial childhood tumor. "Via interacting with CDC16, it can inhibit proliferation and promote differentiation of neuroblastoma cells." (PMID 40149013, 2025). "All these observations suggest that c-Jun inhibits G1/S transition and induces cell cycle arrest at G1 phase whereas CDC16 promotes cell cycle progression in neuroblastoma cells." (PMID 40149013, 2025). "Furthermore, EdU proliferation assay and transwell experiment showed that c-Jun overexpression inhibited neuroblastoma cell proliferation and migration via interacting and sequestering CDC16." (PMID 40149013, 2025).
cancer (6 papers, 2011 to 2022). A tumor composed of atypical neoplastic, often pleomorphic cells that invade other tissues. "Several genes located in 13q34 have been associated with a worse prognosis in other cancers, including CUL4A and TFDP1, IRS2 and CDC16." (PMID 35887382, 2022). "The third group contains four mitotic proteins (ANAPC5, CDC16, CDC20, CDC27) and shRNAs targeting these mitotic genes are predicted to sensitize cancer cells to GSK461364A." (PMID 22248814, 2011). "In addition, mutations have been observed in several APC subunit genes (APC3, APC6/CDC16, and APC8/CDC23) in cancer cells." (PMID 29954095, 2018).
tumor (6 papers, 2005 to 2022). "We found high levels of CDC16 and UBE2T associated with tumor tissues with intestinal and diffuse GC, respectively." (PMID 33351778, 2020). "The TBC (Tre-2/Bub2/Cdc16, TBC) structural domain is now considered as one of the factors potentially regulating tumor progression." (PMID 35918393, 2022). "In this work, qPCR and western blot results revealed a significant increase in expression levels of TTLL12, MZT2B, CDC16 and UBE2T in GC tumor samples of diffuse and intestinal-type, when compared with normal gastric tissues." (PMID 33351778, 2020). "We identified increased levels of TTLL12, CDC16 and UBE2T in tumor samples from 103 patients with diffuse GC (M1) (p <0.001 for all analyzes)." (PMID 33351778, 2020). "Likewise, we identified an increase in mRNA and protein levels in tumor samples from 110 patients with intestinal GC (M1), for MZT2B and CDC16 (p <0.001 for all analyzes)." (PMID 33351778, 2020).
neurodevelopmental disorder (2 papers, 2021). A behavioral and cognitive disorder with onset during the developmental period that involves impaired or aberrant development of intellectual, motor, or social functions. "Members of the Tre2/Bub2/Cdc16 (TBC), lysin motif (LysM), domain catalytic (TLDc) protein family are associated with multiple neurodevelopmental disorders, although their exact roles in disease remain unclear." (PMID 33340069, 2021). "CDC16 has a connection with multiple neurodevelopmental disorders." (PMID 34970268, 2021).
kidney disease (1 paper, 2025). "To validate the potential genes is functionally in kidney disease, we choose whole genes (CDC16, CDC20, CDC27, MAD2L1, ANAPC1, ANAPC7, BUB1B) from first highest score subnetwork obtained from Cytoscape MCODE plugin from upregulated genes PPI as hub genes." (PMID 40034749, 2025).
CDC16 also shares sentences with these, for which no sentence is quoted: adenocarcinoma (1 paper); bladder cancer (1); cervical cancer (1); chronic kidney disease (1); early infantile epileptic encephalopathy (1); focal segmental glomerulosclerosis (1); hepatic cancer (1); infection (1); ovarian carcinoma (1); thyroid cancer (1).